RN7SKP19 (RN7SK pseudogene 19)
Gene: Miscellaneous RNA gene on chromosome 1 (73,191,604 to 73,191,855, reverse strand). Ensembl gene ENSG00000251825.
Homologues: Orthologues: chimpanzee 7SK (99% identical), mouse Gm56408 (49% identical). Paralogues in human: 7SK (65% identical), RN7SKP79 (64% identical), RN7SKP160 (63% identical), RN7SKP189 (63% identical), RN7SKP285 (63% identical), RN7SKP78 (63% identical), RN7SKP133 (63% identical), RN7SKP174 (63% identical), RN7SKP217 (63% identical), RN7SKP240 (63% identical), RN7SKP176 (62% identical), RN7SKP185 (62% identical), and 283 more.
Diseases named in the same sentence as RN7SKP19 in open-access papers:
RN7SKP19 is named in the same sentence as 2 diseases in open-access papers, as found by Europe PMC text mining. Sharing a sentence is not in itself a finding about the gene and the disease. The quoted sentences say what the papers report.
anxiety disorder (1 paper, 2021). A category of psychiatric disorders which are characterized by anxious feelings or fear often accompanied by physical symptoms associated with anxiety. "Furthermore, it has to be noted that non-coding LINC01360 and RN7SKP19 pseudogene in the region associated with depression and anxiety disorder in GWASs." (PMID 34972135, 2021).
RN7SKP19 also shares sentences with these, for which no sentence is quoted: depression (1 paper).